INS (insulin)
Diseases named in the same sentence as INS in open-access papers (continued):
Sharing a sentence is not in itself a finding about the gene and the disease.
lipodystrophy (continued). "To investigate whether the loss of adipose tissue mass due to advanced lipodystrophy and the absence of the lipolytic fasting response translate into improved glucose utilization, we investigated glucose tolerance and insulin sensitivity of HFD-fed AHKO mice at different age." (PMID 33692445, 2021). "Insulin correlated positively with SHBG in the insulin signaling subgroup, but negatively in lipodystrophy." (PMID 33901270, 2021). "Our genetic findings suggest that CAV1 might also have a role in human adipose, insulin and triglyceride metabolism, albeit only two frameshift mutations in CAV1 were found among 60 lipodystrophic patients with a normal coding sequence of known lipodystrophy genes." (PMID 18237401, 2008). "Among the lipodystrophy patients, the peak GH response to GHRH-arginine was significantly predicted by VAT (P = 0.008), FFA (P = 0.04) and insulin level (P = 0.007) in regression modeling." (PMID 17597538, 2007). "Additional lipodystrophy has been reported in a specific CLA isomer at these higher doses, which may impact fatty liver and insulin sensitivity." (PMID 41567914, 2025). "Mice lacking Schnurri-2 showed a reduced body weight and epidydimal WAT mass with a decrease in the size but not in the number of adipocytes; however, insulin sensitivity and glucose tolerance were increased despite lipodystrophy." (PMID 38727299, 2024). "In this study, being from a family that cannot buy insulin when there is no free supply and presence of lipodystrophy at insulin injection sites were identified as predictors of poor glycemic control." (PMID 35705956, 2022). "Interestingly, with advanced lipodystrophy but reversed fatty liver phenotype, at the age of 30–40 weeks, AHKO mice became more glucose tolerant and insulin sensitive compared to age-matched control mice." (PMID 33692445, 2021). "Hyperandrogenemia occurs irrespective of IR etiology, being seen in insulin signaling disorders and lipodystrophy alike, and ovarian histopathology is indistinguishable from PCOS in each of these groups." (PMID 33901270, 2021). "Many participants acknowledged that they had lipodystrophy because they do not use all available body sites for insulin application." (PMID 30291061, 2017). "We recently performed a study investigating the effect of 16 weeks supervised endurance and resistance training on insulin sensitivity, measured by the euglycemic–hyperinsulinemic clamp technique with tracer infusion, in male HIV-infected patients with lipodystrophy." (PMID 24303139, 2013). "Patients with clinical lipodystrophy (CL) had higher plasma glucose levels than patients without CL, without significant differences in plasma insulin levels, A1c, HOMA-IR, HOMA-B, QUICKI, or MATSUDA index." (PMID 22866963, 2012). "Insulin resistance (defined byfasting insulin concentration, oral glucose tolerance test, or clamp studies)without reference to lipodystrophy was the inclusion criteria in three studies." (PMID 19096512, 2009). "Recombinant leptin therapy helps improve insulin sensitivity, reduce circulating triglyceride concentrations, and decrease liver volume in patients with lipodystrophy; however, leptin therapy does not adequately address all the metabolic perturbations for reasons that are incompletely understood." (PMID 40663389, 2025). "In addition, insulin-induced Akt phosphorylation was slightly decreased in the liver and skeletal muscle of HFD-fed PpargC/- mice, suggesting that the liver and skeletal muscle were affected by a high nutrient load in mice with partial lipodystrophy." (PMID 36835312, 2023). "Among patients with lipodystrophy, 45% (67/150) and 1.3% (2/150) had an SHBG level below or above the normal range, respectively; these proportions were 8% (4/49) and 27% (13/49) among patients with insulin signaling disorders, and 52% (11/21) and 0% (0/21) among patients with idiopathic SIR." (PMID 33901270, 2021).
lipodystrophy (continued). "Lipodystrophy in females is frequently accompanied by PCOS, and the main link between these two conditions is the severe IR state, and specifically, the ‘partial’ IR state, which means that some tissues are severely insulin resistant, particularly those involved in the metabolic effects of insulin." (PMID 30131000, 2018). "Adiponectin had been found to promote fat accumulation in adipose tissues and to improve insulin sensitivity in leptin-resistant mice, which could explain the hypoglycemic phenotype of Sik3−/− mice, but not their lipodystrophy." (PMID 22662228, 2012). "In addition, Tsuboyama-Kasaoka, Takahashi, Tnemura, Kim, Tnage, Okuyama, Kasai, Ikemoto, and Ezaki showed preliminary data indicating that leptin infusion lowers the levels of serum insulin and attenuates hepatocyte fat deposition in CLA-fed lipodystrophy model mice." (PMID 18348717, 2008). "Interestingly in individuals without T2D, (n = 895,990), we observed that the lipodystrophy (P < 10−17), adiposity (P < 10−8), and elevated insulin secretion (P < 10−9) genetic clusters maintained their associations with increased CAD and MI risk (OR 1.06, P < 10−12)." (PMID 37790568, 2023). "It is important to mention that plasma LPS levels were higher in HIV patients treated with HAART with and without lipodystrophy suggesting that circulating LPS may have a role in the reduced insulin sensitivity in these patients, probably in a manner independent of fat storage." (PMID 29434676, 2018). "While randomized trials in lipodystrophy population are lacking, clinical experience and observational data suggest that concentrated insulin formulations may be particularly useful for delivering the required insulin amounts in patients with very high insulin requirements." (PMID 40892266, 2025). "Given the severe lipodystrophy in our mouse model, our data also reveal that GLP-1 receptor activation can improve insulin sensitivity and metabolic health independent of adipose tissue, providing additional novel mechanistic insight." (PMID 38745956, 2024). "Patients with lipodystrophy had higher glucose and insulin at 0 minutes, and insulin at 120 minutes on OGTT, HOMA, non-HDL cholesterol, triglycerides, uric acid, and lactates, than patients without lipodystrophy." (PMID 24958511, 2014). "Patients with lipodystrophy defined by FMR had higher plasma glucose and insulin levels, A1c, HOMA-IR, QUICKI and MATSUDA than patients without lipodystrophy, without differences in HOMA-B." (PMID 22866963, 2012).
hypothyroidism (173 papers, 2008 to 2026). Abnormally low levels of thyroid hormone. "T1DM primarily targets insulin‐producing β‐cells in the pancreas, whereas autoimmune thyroiditis affects thyroid tissue, causing hypothyroidism or hyperthyroidism." (PMID 41573056, 2026). "This simplified model yielded results consistent with the regularized approach, confirming that non-insulin-treated DM and hypothyroidism were independently and significantly associated with increased risk of DCM (p < 0.001)." (PMID 41153651, 2025). "In women, the decreasing insulin sensitivity is associated with the decreased metabolic rate of thyroid hormones, which triggers hypothyroidism and goiter." (PMID 40129592, 2025). "Due to the association between insulin residence and reproductive disorder with both hypothyroidism and PCOS, patients with overt hypothyroidism are excluded from being diagnosed with PCOS." (PMID 36673125, 2023). "Hypothyroidism is associated with a decrease of normal glucose-stimulated insulin secretion by the beta-cells, while an increase of insulin secretion has been reported in hyperthyroidism." (PMID 33801253, 2021). "The association of hypothyroidism and compromised insulin‐stimulated glucose uptake in muscle and adipose tissue has been documented on animals and humans." (PMID 33048427, 2020). "Several reports have determined that maternal hypothyroidism predisposes the offspring to exhibit limited insulin secretion and to develop glucose intolerance, increasing the risk of T2DM in the offspring." (PMID 33048427, 2020). "About 80% of FA children and adults show at least one endocrine defect, including GH deficiency, atypical glucose or insulin metabolism, dyslipidemia, hypothyroidism, pubertal delay, hypogonadism, or impaired fertility." (PMID 32962238, 2020). "A short stature mainly results from endocrine defects that about 80% of FA patients show: growth hormone (GH) deficiency, abnormal glucose or insulin metabolism, hypothyroidism, etc. contribute to worsening the life quality of FA patients." (PMID 32962238, 2020). "In contrast, systemic hypothyroidism is associated with reduced hepatic gluconeogenesis and enhanced insulin sensitivity, as demonstrated by the onset of a hypoglycemic state after an insulin injection." (PMID 30254607, 2018). "IR in the setting of hypothyroidism has been documented and is associated with decreased responsiveness of glucose uptake in muscle and adipose tissue to insulin, as well as decreased glycogen synthesis in skeletal muscle in both animal and human studies." (PMID 23431294, 2013). "Overt hypothyroidism has been linked to changes in glucose metabolism and insulin sensitivity." (PMID 40100858, 2025). "As a result, hypothyroidism inhibits fat loss as blood insulin levels rise." (PMID 37626767, 2023). "In conclusion, maternal hypothyroidism can slow intrauterine growth of a fetus and cause low expression of TRβ in the pancreas, both of which result in deficiencies in pancreas' cell proliferation and insulin synthesis." (PMID 30918900, 2019). "More recently, hypothyroidism has also been linked to decreased insulin sensitivity." (PMID 21941681, 2011). "Hypothyroidism has been identified as a potential cause of hypoglycemia and, as such, should be monitored in cases of unexplained low blood glucose levels; on the opposite end of the spectrum, some, but not all, investigations have discovered a link between hypothyroidism and insulin resistance." (PMID 37809188, 2023). "Additionally, thyroid hormones may act as antagonists in the liver so thyroid hormone deficiency may decrease glucose production and increase insulin resistance, suggesting a possible role of hypothyroidism in the pathogenesis of PCOS." (PMID 34521474, 2021). "Hypothyroidism is characterised by attenuated basal plasma insulin levels, increased glucose‐induced insulin secretion, insulin resistance and weight gain." (PMID 41317333, 2026).
hypothyroidism (continued). "Hypothyroidism, characterized by low levels of circulating thyroid hormones, has also been demonstrated to lead to decreased peripheral insulin sensitivity and glucose intolerance." (PMID 39831884, 2025). "Thyroid disorders affect insulin function differently: hypothyroidism reduces β-cell insulin sectretion in response to glucose, while hyperthyroidism increases insulin resistance." (PMID 39940455, 2025). "Thyroid hormone abnormalities were noted, such as hypothyroidism or hyperthyroidism, which can exacerbate glycaemia control challenges in diabetic patients by altering insulin sensitivity and glucose metabolism." (PMID 40731899, 2025). "Hypothyroidism, present in 72.7% of our DS cohort, is known to influence lipid profiles, body composition, insulin sensitivity, and inflammatory markers." (PMID 41234441, 2025). "Hypothyroidism reduces insulin sensitivity, worsening glycemic control, while hyperthyroidism increases insulin resistance and hepatic glucose output." (PMID 40091940, 2025). "Epidemiological studies in human cohorts have observed a link between MASLD and hypothyroidism, where the main role of thyroid hormones in lipid metabolism (lipid export and oxidation) and hepatic insulin sensitivity has been proven on multiple occasions." (PMID 40217851, 2025). "Another study confirmed that hypothyroidism leads to decreased synthesis and release of insulin and insulin resistance." (PMID 40563510, 2025). "Post-treatment stabilization required basal-bolus insulin at discharge, with continued levothyroxine for hypothyroidism." (PMID 40388765, 2025). "Significant differences were observed when comparing insulin doses between diabetic dogs with hypercortisolism and hypothyroidism at t1 and t2 (P<0.01)." (PMID 39535393, 2024). "For example, in hypothyroidism there is a decrease in insulin production by beta cells, and muscle cells develop less insulin sensitivity." (PMID 39258119, 2024). "Although present in women with hypothyroidism of different origins, the improvement in insulin sensitivity was less pronounced if subclinical hypothyroidism was induced by thyroid autoimmunity." (PMID 38051473, 2024). "The aim of this study was to compare insulin requirements and serum fructosamine concentrations in diabetic dogs with naturally‐occurring hypercortisolism and hypothyroidism." (PMID 39535393, 2024). "Dyslipidaemia observed in cases with hypothyroidism is due to the metabolic derangements in functions of insulin and increased oxidative stress in the body." (PMID 36819139, 2023). "Regarding beta cell function, glucose-induced insulin secretion is increased, and several studies have shown that insulin levels are elevated in hypothyroidism." (PMID 38004062, 2023). "There is evidence that hypothyroidism can reduce glucose absorption from the gastrointestinal tract, increase insulin levels, and suppress hepatic glucose production." (PMID 37946276, 2023). "Oral medications, such as Bromocript 2.5 mg quaque die (Qd) for hyperprolactinemia, Euthyrox (Merck) 112.5 μg (Qd) for hypothyroidism, metformin 0.5 g bis in die (Bid) for insulin resistance, were used long-term under MDT monitoring." (PMID 37929040, 2023). "Moderate I2 concentrations prevented the increase in insulin and GLUT4 expression caused by hypothyroidism and retained the PPARG amount (2.1 + 0.07)." (PMID 37834351, 2023). "Pharmacological hypothyroidism modifies insulin secretion and the expression of GLUT4, hexokinase, and glucokinase." (PMID 37834351, 2023). "Hypothyroidism reduces the amount of glucose that fat cells can take up in response to insulin, but insulin can still stop fat breakdown in the fat cell, limiting cell shrinkage." (PMID 37626767, 2023). "The nodes of insulin and hypothyroidism havesufficient connections to AD to be considered relevant but are distant enough,domain wise, to showcase SemNet’s flexibility in exploring more nuanced,and lesser cited multi-factorial disease etiology." (PMID 35936510, 2022).
hypothyroidism (continued). "Importantly, hypothyroidism, both overt and subclinical disease, was also associated with a deterioration of glucose metabolism and elevated whole-body IR; moreover, it appeared to be subject to an increased risk of hypoglycemia as a consequence of the mismatch between insulin and glycemic levels." (PMID 35740085, 2022). "Hypothyroidism patients have inadequate TH secretion, which is precisely related to the secretion of insulin in adipose tissue and the stimulation of lipolysis by adrenal gland." (PMID 33791302, 2021). "Hypothyroidism resulted in a decrease in insulin production via beta cells whereas hyperthyroidism led to an increase in beta-cell responsiveness to catecholamine or glucose due to increased beta-cell mass." (PMID 35106234, 2021). "As for hypothyroidism, glucose metabolism is affected via a reduced rate of liver glucose production and the decrease in insulin requirement." (PMID 34670571, 2021). "On the other hand, in the experimental model, it has been observed that in hypothyroidism glucose uptake in adipose tissue and in muscle is resistant to insulin, resulting in elevated serum insulin concentration." (PMID 30945110, 2019). "The FG rats showed a significant elevation of basal T4 levels, but in the steady state period the insulin infusion reduces T4, possibly through stimulating its transformation into T3 due to elevated GH that promotes hypothyroidism." (PMID 31080828, 2019). "To further characterize the effects of hypothyroidism on mitochondria and IR, we tested proteins involved in mitochondrial oxidation and insulin signal transduction by Western blot analysis." (PMID 29784871, 2018). "Various studies reveal that patients with hypothyroidism have an increased level of the hormone insulin." (PMID 29784871, 2018). "Thyroid hormone is a key determinant of glucose homeostasis by regulating the balance of insulin, but hypothyroidism can disrupt hormonal balances and alter glucose and lipid metabolism to lead to insulin resistance (IR)." (PMID 29784871, 2018). "In a recent study, propylthiouracil-induced hypothyroidism in male rats also led to impaired glucose tolerance due to reduced glucose-stimulated insulin secretion." (PMID 30013597, 2018). "The extent to which growth patterns during hypothyroidism relate to changes in insulin signalling pathways in these fetal organs, however, remains to be established." (PMID 28144955, 2017). "Hypothyroidism in the sheep fetus resulted in an asymmetric pattern of organ growth, pancreatic beta cell hyperplasia, and elevated plasma insulin and leptin concentrations." (PMID 28144955, 2017). "Treatment of hypothyroidism has been shown to restore insulin sensitivity and the secretion of glucoregulatory hormones." (PMID 27686165, 2016). "In spite of the discrepancy regarding the effect of hypothyroidism on the concentration of glucose and insulin, this hormonal condition affects the number and proliferation of islet cells and the content of extracellular matrix into the islets." (PMID 26175757, 2015). "In spite of the controverted effects of hypothyroidism on serum glucose and insulin concentrations, the number and proliferation of Langerhans islet cells as well as the presence of extracellular matrix are affected depending on the islet size." (PMID 26175757, 2015). "The aim of this study was therefore to determine the possible mechanisms by which hypothyroidism impairs insulin secretion in rats." (PMID 26132582, 2015). "Despite much larger amount of insulin released into the blood after glucose ingestion (IRIauc) in women with hypothyroidism, the glucose concentration in blood was high." (PMID 24711817, 2014). "Following their studies on patients with hypothyroidism, Handisurya and Stanicka have concluded that hypothyroidism makes glucose inaccessible to insulin." (PMID 25364704, 2014).